TNF (tumor necrosis factor)
Diseases named in the same sentence as TNF in open-access papers (continued):
Sharing a sentence is not in itself a finding about the gene and the disease.
uveitis (continued). "Compared with placebo, anti-TNF therapy including ETA was associated with significantly fewer flares and new onset of uveitis, but were not significant efficacious for treating IBD in AS patients." (PMID 25888248, 2015). "Six trials reported on uveitis that occurred in 7 patients in the anti-TNF therapy group and 16 in the placebo group; 5 trials reported on IBD that occurred in 5 patients in the anti-TNF therapy group and 4 in the placebo group." (PMID 25888248, 2015). "The occurrence of uveitis in patients that never had eye involvement or the relapse of uveitis is described during anti-TNFα treatment." (PMID 24991219, 2014). "A recent survey of US pediatric rheumatologists on the treatment of patients with JIA revealed that anti-TNF agents were used more often in those with versus without co-morbid uveitis." (PMID 24886032, 2014). "Some cases had benefit with the switch to another TNF blocker, but in most reported cases uveitis was solved without anti-TNFα interruption." (PMID 24991219, 2014). "In sum, further randomized, controlled trials are required to adequately assess the actual benefits and safety profile in the long term of anti-TNF agents in BD, sarcoidosis, and noninfectious uveitis." (PMID 23983404, 2013). "Vitreous samples from 60 patients with PIOL (n = 17), OCL (n = 9), uveitis (n = 23) or retinal detachment (RD) without hemorrhage (n = 11) were analyzed for IL-2, IL-4, IL-6, IL-10, IFNγ, and TNFα concentrations by CBA." (PMID 23405064, 2013). "The aim of this paper is to discuss the available data regarding the off-label uses of the anti-TNF agents in three specific frequent disorders: Behçet's disease, sarcoidosis, and noninfectious uveitis." (PMID 23983404, 2013). "No specific adverse effects of anti-TNF therapy when treating BD, sarcoidosis, and noninfectious uveitis have been reported, other than those already known to these agents." (PMID 23983404, 2013). "Although anti-TNFα therapies translate effectively to the clinic for uveitis, this is not the case for patients with MS in whom anti-TNFα agents worsen disease and precipitate demyelination in others." (PMID 23378732, 2013). "The experimental models of uveitis (experimental autoimmune uveoretinitis, EAU) and MS (experimental autoimmune encephalomyelitis, EAE) share many common features; in particular, the detrimental role of tumor necrosis factor-α (TNFα)." (PMID 23378732, 2013). "The authors concluded that these results suggest a relationship with the development of agent-specific uveitis rather than with the anti-TNF blockers on the whole." (PMID 23983404, 2013). "TNF-α is a key cytokine involved in the pathogenesis of many inflammatory disorders, including non-infectious uveitis." (PMID 22454752, 2011). "Conventional treatment for non-infectious uveitis is non-specific and includes the frequent use of topical and/or systemic corticosteroids and other immunosuppressive agents or biologics, such as anti-tumor necrosis factor-α (TNF-α) antibodies." (PMID 40718791, 2025). "We conducted a network meta-analysis (NMA) to assess the impact of anti-TNF-α (adalimumab, etanercept, golimumab, and infliximab), IL-17 inhibitors (secukinumab, bimekizumab, and ixekizumab), and JAK inhibitors (tofacitinib and upadacitinib) on new-onset and recurrent uveitis." (PMID 40621455, 2025). "A systematic review on TNF inhibitor optimization, precisely dose spacing in non-infectious uveitis, concluded that it is difficult to draw definitive conclusions regarding the effects of optimization on uveitis." (PMID 41007651, 2025). "Additionally, TNF-α has been identified to elevate the production of vascular endothelial growth factor (VEGF) in choroidal endothelial cells, with VEGF being accountable for macular edema in individuals with uveitis." (PMID 39157460, 2024). "In 2016, it was approved by the US FDA as the first anti-TNF-α drug for non-infectious uveitis." (PMID 39062219, 2024).
uveitis (continued). "- The choice of first-line biological treatment in peripheral forms (anti-TNF, anti-IL17, anti-IL23, generally anti-TNF) must take into account the form of SpA (PsA), the presence or absence of uveitis or IBD, patient’s profile, and the decision must be shared between the patient and the physician." (PMID 37654637, 2023). "We believe that JAK inhibitors could be another treatment option for noninfectious uveitis in patients who do not respond to conventional anti-TNF-α inhibitors (such as adalimumab)." (PMID 35115933, 2022). "Thus, tumor necrosis factor-alpha (TNF-α) inhibitors such as adalimumab have also been approved for the treatment of noninfectious uveitis." (PMID 36451402, 2022). "However, there are no published studies in patients with uveitis to date regarding the effect of anti-TNF therapy on microbiome status." (PMID 35806031, 2022). "Furthermore, during a 2-year treatment period, 40% of JIA-uveitis patients receiving adalimumab and 80% receiving the anti-TNFα monoclonal antibody, infliximab, did not achieve clinical remission." (PMID 34627340, 2021). "BD patients with active uveitis have been shown to have significantly higher levels of TNF-α than those without any eye involvement for 3 months and anti-TNF-α therapy (such as Infliximab) has been helpful in controlling active episodes of uveitis in BD as well as oral and genital ulceration." (PMID 35003055, 2021). "Therefore, counteracting TNF-α with TNF-α inhibitors is a reliable strategy in the treatment of non-infectious uveitis." (PMID 35096888, 2021). "Thus, in this review, we aimed to provide a background of the role of TNF-α in the immunopathogenesis of uveitis and an account of the progress from bench to clinical research progress to better guide TNF-α-based therapeutics for uveitis." (PMID 34795583, 2021). "Current available non–anti-TNF Biologics treatments in non-infectious uveitis." (PMID 32508634, 2020). "In addition, in the aqueous humor of BD patients with uveitis, elevated TNF-α levels were observed, compared to healthy controls or BD patients without uveitis." (PMID 32349254, 2020). "Current anti-TNF-α available treatments in non-infectious uveitis." (PMID 32508634, 2020). "Indeed, biological drugs anti-TNFα have been proven to be effective in non-infectious uveitis and have been approved by FDA and EMEA for therapy." (PMID 32210963, 2020). "According to our findings, VEGF, TNFα, and IFNγ had no role in BD uveitis." (PMID 28468317, 2017). "However, at present, there are no RCT data available demonstrating the efficacy of anti‐TNF therapy in the reduction of uveitis flares in an axial SpA population (i.e., containing both AS and nr‐axial SpA patients)." (PMID 26815944, 2016). "However, Subgroup analysis showed the receptor fusion protein ETA was more efficacious than placebo for uveitis in this patient population, whereas monoclonal anti-TNF antibodies were not." (PMID 25888248, 2015). "However, percent detectable of IL-10, IL-31, IFN-γ, sCD40L, and TNFα, and mean vitreous levels of IL-6, IL-10, IL-31, IFN-γ, sCD40L, and TNFα were significantly higher in eyes with uveitis than in those with ERM or MH (data not shown)." (PMID 26352837, 2015). "Nevertheless, uveitis seems to be specifically associated with ETA and not with all anti-TNFα." (PMID 24991219, 2014). "Recently published case series suggested that in case of refractory uveitis with lack of initial clinical response to one anti-TNF-α agent, switching to another one could achieve control of intraocular inflammation." (PMID 23587261, 2013). "Although the systemic use of TNF-α inhibitors is an appropriate off-label alternative to “traditional” immunosuppressive and immune-modulatory treatments in noninfectious uveitis, its use in vascular and neovascular retinal diseases has not yet been thoroughly examined." (PMID 22737386, 2012).
uveitis (continued). "TNF-α blockers are widely used in ophthalmology as an off-label alternative to “traditional” immunosuppressive and immune-modulatory treatments in noninfectious uveitis." (PMID 22737386, 2012). "For example, the TNFα inhibitor, etanercept, diminishes arthritic symptoms in a subgroup of patients with AS, but it does not always have comparable beneficial effects for uveitis in the same patients; or it can even lead to increased severity of uveitis." (PMID 22269151, 2012). "The treatment strategy for ICI uveitis could consist of topical corticosteroid injection (STTA or intravitreal injection), systemic corticosteroid administration, and/or discontinuation of ICIs or might include anti-IL-6 and tumor necrosis factor-alpha treatment." (PMID 40444081, 2025). "Despite this trial not meeting the threshold required to justify a larger phase 3 trial, several patients responded to treatment; as such, tocilzumab might still be a therapeutic option in some children with uveitis refractory to anti-TNF drugs, given the absence of other treatment options." (PMID 32280950, 2020). "Subgroup analysis for uveitis in patients with AS showed TNF receptor fusion proteins to be more efficacious than placebo (OR: 0.30, 95% CI: 0.09–0.94, P = 0.04); whereas monoclonal anti-TNF antibodies did not significant differ from placebo (OR: 0.43, 95% CI: 0.12–1.49, P = 0.18)." (PMID 25888248, 2015). "Similarly, Th17 cells induced from a sarcoidosis uveitis patient upregulated the IL-17 production when recombinant TNF-α was added to cultures (data not shown), suggesting that TNF-α may be generally essential for Th17 differentiation in inflammatory diseases." (PMID 22546542, 2012). "By modulating the TNF-α–mediated inflammatory cascade, ADA has demonstrated clinical efficacy as a steroid-sparing agent in noninfectious uveitis." (PMID 41471337, 2025). "Adalimumab, an anti-tumor necrosis factor (TNF) mAb, has been approved for the treatment of noninfectious uveitis, providing an alternative for patients who are unresponsive to conventional immunosuppressive therapies." (PMID 39449328, 2024). "Adalimumab, the only TNF inhibitor approved by the FDA, was ineffective in treating non-infectious uveitis in all cases." (PMID 39407875, 2024). "Although we have not examined the expression of TNF-α in this animal model, there are previous reports on the relation between TNF-α and uveitis." (PMID 38015876, 2023). "Results revealed that levels of IL-6, IL-10, TNF-α, FLT3l, PDGF-AB/BB, and sCD40L were significantly increased in both OT and non-OT uveitis patients, compared with the control group levels." (PMID 35646978, 2022). "Tocilizumab demonstrated promising outcomes in five adult BD cases with refractory uveitis who previously failed to respond to IFN-alpha and anti-TNF treatment." (PMID 35268369, 2022). "Comparison of classical monocytes between HC and uveitis patients revealed that common monocytic markers, e.g., CCR2, CX3CR1, HLA-DR, HLA-ABC, IL-6, IL-1β, and TNF-α were not affected (data not shown)." (PMID 30105034, 2018). "Biologicals such as TNF-α inhibitors and IFN-α have expanded the treatment options for chronic non-infectious uveitis in the last decades, albeit the financial consequences of this development remain to be elucidated." (PMID 30873449, 2015). "Investigation using this model has ultimately led to the approval by the Food and Drug Administration of tumor necrosis factor-α (TNF-α) inhibitor as the first targeted, corticosteroid-sparing biologic for treating noninfectious uveitis involving the intermediate or posterior eye." (PMID 40323267, 2025). "In addition, there were significant increases in TNF-α and IFN-γ (Th1) in non-OT uveitis group than that in controls, but there were no significant different in IL-17." (PMID 35646978, 2022).
Hepatitis (374 papers, 2007 to 2026). Inflammation of the liver. "TNF-α causes damage to hepatocytes and induces the production of IL-1β and IL-6, thereby causing hepatocyte apoptosis and liver inflammation." (PMID 38999886, 2024). "Hepatitis and drug-induced liver injury models showed that hepatic damage is frequently associated with immune cell activation and TNF-α and IFN-γ function as the critical cytokines in the pathogenesis." (PMID 38448543, 2024). "In hepatic diseases such as hepatitis and cirrhosis, elevated systemic and hepatic TNF-α levels have been linked to vascular dysfunction." (PMID 39635433, 2024). "Liver immune cells and the proinflammatory cytokines they produce, including Interleukin 6 (IL-6), Tumor Necrosis Factor Alpha (TNFα) and Interleukin 1 beta (IL-1β), have all been implicated in driving behavioral changes in the setting of liver inflammation." (PMID 37521690, 2023). "These inflammatory cytokines, such as TNF-α, IL-6, and C-reactive protein, can induce liver inflammation and fibrosis, causing liver cell damage and interfering with liver function." (PMID 38076231, 2023). "According to our findings, a low-vitamin B12 diet raises proinflammatory cytokines similar to TNF-a and IL-6, activating Kupffer cells (liver macrophages) and causing liver inflammation, whereas rosella extract treatment lowers proinflammatory cytokines." (PMID 37374248, 2023). "ConA‐induced hepatitis is mediated by T cell‐derived interferon‐γ and KC‐deriver TNF‐α, causing massive liver necrosis with dense infiltration of leukocytes and release of the ALT and AST from the cytoplasm of hepatocytes into the blood." (PMID 35759238, 2022). "Some post-marketing reports have described several hepatic reactions, hepatitis and acute liver failures in patients treated with TNF-α inhibitors (mainly with infliximab), even though the risk is very slight and casual relationship has not established." (PMID 33141869, 2020). "Studies have associated the induction of hepatitis with innate immunity and acquired type 1 pro-inflammatory response including TNF-α, IL-1β, IL-6, and IL-12." (PMID 31611801, 2019). "Ameliorated MCMV-induced hepatitis in Gal-3 KO mice treated with infliximab supports the role of TNF-α in enhanced disease in Gal-3 deficient animals." (PMID 30800112, 2019). "Previous reports have focused on the great impact of TNF-α on Con A-induced hepatitis and how it is linked to activation of other cytokines." (PMID 29643811, 2018). "Both T cells and macrophages play key roles in ConA-mediated hepatitis by producing TNFα and IFNγ, both of which cause liver injury." (PMID 30462657, 2018). "Active carriers should be treated firstly for their active hepatitis with nucleos(t)ide analogues (NAs), such as lamivudine, entecavir or adefovir-pipivoxil, and then with anti-TNF-α for their underlining disease." (PMID 30060508, 2018). "Although it is well established that TNFα contributes to hepatitis, liver failure and associated hepatocarcinogenesis via the regulation of inflammation, its pro-apoptotic role in the liver has remained enigmatic." (PMID 30185788, 2018). "In the d-galN/LPS model, lethality is mostly caused by a caspase 3-dependent fulminant apoptotic hepatitis induced by TNF-α." (PMID 28659918, 2017). "Adipokines, such as IL-6 and TNF-α, produced during chronic inflammation of hypertrophied white adipose tissue are thought to cause hepatocyte fat accumulation and liver inflammation." (PMID 29022011, 2017). "It is well known that the progression of hepatitis is closely associated with inflammatory factors including TNF-α, IFN-γ, IL-1β, IL-2, IL6 and iNOS." (PMID 27035150, 2016). "Most strikingly, Bad-deficient animals were protected from the lethal effects of hepatitis elicited by D-GalN priming and subsequent TNF injection." (PMID 25611386, 2015). "It is a common perspective that the progress of hepatitis is associated with a series of proinflammatory cytokines such as IL-2, IL-6, IL-1β and TNF-α." (PMID 24498418, 2014).
Hepatitis (continued). "Together, these data demonstrated that the protective role of salidroside pretreatment in Con A-induced hepatitis is associated with reduction of TNF-α, IFN-γ, and IL-6." (PMID 24808635, 2014). "TNF-α, IL1β and IL-6 are the cytokines most commonly associated with liver inflammation, while CD64 and CD68 are markers of Kupffer cell activation." (PMID 23755290, 2013). "Previous studies have demonstrated that ORM1 has the capacity to inhibit TNFα activity and protects mice from TNFα -induced lethality or hepatitis caused by TNFα and galactosamine." (PMID 22916107, 2012). "Moreover, the over-expression of inflammatory factors such as interleukin-1β (IL-1β), interleukin-6 (IL-6) and tumor necrosis factor-alpha (TNF-α) induced by FAdV-4 caused hepatitis and further necrosis." (PMID 35590365, 2022). "In addition, several cytokines are implicated in the pathogenesis of ConA-induced hepatitis, of which TNF-α, IFN-γ, TGF-β are the most important." (PMID 36188529, 2022). "Associations with INH hepatitis and polymorphisms in the tumor necrosis factor-alpha (TNF-α) gene and the class II major histocompatibility complex (MHC) allele HLA-DQB1∗02:01 have also been described, although the effect and sample sizes in these studies were small." (PMID 39959342, 2021). "Among these cytokines, TNF-α and IL-1β could be the critical mediators for development of ConA-induced hepatitis, since TNF-α-deficient mice and NLRP3- and caspase-1-deficient mice that do not produce IL-1β are almost protected from ConA-mediated liver damage." (PMID 33809904, 2021). "In TNF-induced lethal hepatitis, MMP-8-deficient mice showed impaired leukocyte influx and neutrophil-specific chemokine release implicating that, rather than influencing the hepatitis-induced hepatocyte necrosis as previously thought, MMP-8 plays a pivotal role in regulating acute inflammation." (PMID 32414178, 2020). "In contrast, Pioglitazone-induced PPARγ activation exacerbated D-galactosamine (GalN)/lipopolysaccharide (LPS) hepatitis associated with an increased production of TNFα by Kupffer cells and increased sensitivity of hepatocytes towards TNFα after in vivo Pioglitazone administration." (PMID 32260486, 2020). "Interestingly, in vivo pharmacological inhibition of LRH-1 also resulted in reduced tumor necrosis factor (TNF) production and associated decreased liver damage in a macrophage- and TNF-dependent mouse model of hepatitis." (PMID 32111818, 2020). "In a model of TNFα treatment-induced apoptosis, it was demonstrated that Nrf2-deficient thymocytes die quickly and Nrf2-deficient mice show severe hepatitis, and Nrf2 can reduce the sensitivity of cells to apoptotic signals by regulating cell oxidative balance." (PMID 31878265, 2019). "Various cytokines, including IFN-γ and TNF-α, are involved in the pathogenesis of Con A-induced hepatitis, so we wondered whether RACK1 deficiency affects cytokine production." (PMID 28572806, 2017). "We hypothesized that astaxanthin could inhibit the rise in TNF-α levels caused by ConA-induced hepatitis, in turn reducing liver damage." (PMID 25761053, 2015). "Moreover, a specific role for IL-6, together with TNF, has been proposed in the pathogenesis of liver inflammation and cancer associated with dietary and genetic obesity." (PMID 24464501, 2014). "The leaked LPS potentiates alcohol-induced liver inflammation and stimulates immune cells such as monocytes, macrophages, T lymphocytes, and dendritic cells to cause the release of pro-inflammatory cytokines, including interleukin (IL)-1β, IL-6, and tumor necrosis factor-alpha (TNF-α)." (PMID 28082989, 2016). "Treated with anti-TNF and methotrexate, she was hospitalized for HSV-2–associated hepatitis and pancreatitis." (PMID 41348319, 2026). "Liver inflammation and fibrosis are regulated by complex immunological pathways, and pro-inflammatory cytokines, such as TNF-α, IL-1 and IL-6." (PMID 40365189, 2025).